TOP2B (DNA topoisomerase II beta)
Diseases named in the same sentence as TOP2B in open-access papers (continued):
Sharing a sentence is not in itself a finding about the gene and the disease.
neuroblastoma (continued). "Remarkably, we found that CX-5461 was between 2- and 4-fold more effective at inhibiting TOP2B, compared to TOP2A (P = 2.8 × 10−4), confirming the broader relevance of this mechanism outside neuroblastoma cells." (PMID 34753908, 2021). "We showed that TOP2B remains overexpressed in neuroblastoma, particularly in younger and neonatal patients and that TOP2B expression is driven higher by MYCN overexpression, explaining the selective activity of CX-5461 against neuroblastoma cells." (PMID 34753908, 2021). "Although the expression of TOP2B was again typically higher in neuroblastoma tumors than normal human tissues, there was clear expression across normal tissues, including cardiac tissues and most strikingly some regions of the brain." (PMID 34753908, 2021). "Although the TOP2B ChIP-seq data was derived from a different neural cell type (glioma rather than neuroblastoma), inspection of the accompanying expression data revealed that most genes of interest from our RNA-seq analysis were also expressed in the glioma cells." (PMID 35831557, 2022).
glioblastoma (5 papers, 2016 to 2023). The most malignant astrocytic tumor (WHO grade IV). "In the present study we show that Top2β, an ATP-dependent enzyme that catalyzes topological changes of DNA, is highly expressed in glioblastoma stem cells." (PMID 27462186, 2016). "Also among the tested cell lines the expression of Top2β was the highest in NCH421k cells, a well-characterized glioblastoma cell line with all the stemness characteristics." (PMID 27462186, 2016). "Thus, we investigated if a particular step of neuronal NMDAR signaling, which might be interesting for cancer therapy, was analogous with glioblastoma cells: The Top2β mediated gene activation via induction of DSBs." (PMID 30841565, 2019). "We suggest that Top2β may represent a new target for gene therapy in glioblastoma." (PMID 27462186, 2016). "In glioblastoma cells, CREB triggers the expression of immediate early genes, such as cFos, by inducing Top2β (topoisomerase IIβ) DNA double-strand breaks (DSB) in their promoter regions." (PMID 36768862, 2023). "Therefore, we analyzed the contribution of iGluRs and Top2β in the induction of DSBs and the expression of the ERG cFos in the LN229 glioblastoma cell line." (PMID 30841565, 2019). "Collectively, our results show that the activation of NMDARs by Glu induces Top2β-mediated DSBs that are independent of cell cycle progression in the glioblastoma cell line LN229." (PMID 30841565, 2019). "Nevertheless, although cultured tumor cell lines from glioblastomas may not fully reflect the genotypes and phenotypes of the respective primary tumors, inhibition of Top2β in G1702 cells led to a reliable downregulation of cFos, which was remarkably more pronounced than in the LN229 cells." (PMID 30841565, 2019).
acute myeloid leukemia (4 papers, 2017 to 2021). Acute myeloid leukemia (AML) is a group of neoplasms arising from precursor cells committed to the myeloid cell-line differentiation. "Patients treated with etoposide can develop acute myeloid leukemia (t-AML) that had been demonstrated as attributing to TOP2B-mediated DNA breaks that disrupt mixed-lineage leukemia (MLL) and MLL-associated genes in human bone marrow cells." (PMID 34359577, 2021). "Song and co-workers showed that TOP2B high expression was correlated with favorable outcome in acute myeloid leukaemia patients." (PMID 28355294, 2017). "It had been shown that etoposide treatment to patients can induce acute myeloid leukemia (t-AML), which is attributed to TOP2B-, but not TOP2A-mediated DNA damage that disrupts the mixed lineage leukemia (MLL) gene and MLL associated genes in benign bone marrow cells." (PMID 33598437, 2020).
glioma (4 papers, 2016 to 2022). A benign or malignant brain and spinal cord tumor that arises from glial cells (astrocytes, oligodendrocytes, ependymal cells). "We show that the depletion of Top2β in glioma stem cells leads to increased sensitivity to a panel of replication stress-inducing drugs." (PMID 27462186, 2016). "Our finding demonstrated higher expression of Top2β in GSCs which are reportedly more abundant in high grade glioma and correlate with worse prognosis." (PMID 27462186, 2016). "Therefore, we posit that there should be a positive correlation of Top2β with malignancy, but future measurements of the expression of Top2β in low grade glioma would be necessary to support this conclusion." (PMID 27462186, 2016). "Top2β-dependent transcriptional regulation of the early response gene cFos in the LN229 and primary GBM cells suggests that the neuronal Top2β-dependent signaling pathway maybe a common phenomenon responsible for promoting malignant growth in glioma cancers." (PMID 30841565, 2019).
lung carcinoma (4 papers, 1993 to 2024). "Therefore, blocking MDM2-mediated TOP2β degradation by RG7112 synergistically suppresses lung cancer cell survival following treatment with VP-16, resulting in an increase in apoptosis and susceptibility to VP-16 treatment." (PMID 38263255, 2024). "Biologically, we established that MDM2-mediated TOP2β degradation increases cancer cell survival, since its inhibition by RG7112 decreases the survival of lung cancer cells synergistically with VP-16 treatment, resulting in increased apoptosis and higher sensitivity to VP-16 treatment." (PMID 38263255, 2024).
schizophrenia (4 papers, 2015 to 2022). A major psychotic disorder characterized by abnormalities in the perception or expression of reality. "We have previously reported an overlap between genes implicated in ASD or schizophrenia and genomic localisation of TOP2B peaks derived from ChIP-seq experiments." (PMID 35831557, 2022).
autism spectrum disorder (3 papers, 2017 to 2022). A spectrum of developmental disorders that includes autism, and Asperger syndrome. "Our findings indicate that Top2β, a gene implicated in neurodevelopmental diseases such as autism spectrum disorders, plays a critical, cell-specific role in the assembly of motor circuits." (PMID 29379870, 2017). "Recently, a heterozygous H58Y substitution in the ATPase domain of human TOP2B was identified from patients with autism spectrum disorder, but its biological significance remains unclear." (PMID 36450898, 2022). "It has been suggested that the transcription of long genes, including autism-spectrum disorder risk genes, is disproportionately affected in the absence of Top2β activity." (PMID 29379870, 2017). "Our results highlight an unexpected specificity for Top2β function and offer support to the idea that Top2β disruption in the nervous system can have subtle, specific effects, manifesting for example as autism spectrum disorders, rather than global dysfunction and wide-spread neuronal cell death." (PMID 29379870, 2017).
bladder cancer (3 papers, 2017 to 2023). "The function of TOP2B in bladder cancer risk or progression currently remains undetermined." (PMID 37666817, 2023). "Another study showed that the DNA methylation of TOP2B has a typical male bias in bladder cancer, and its related drug valrubicin can be used for intravesical treatment of BCG-refractory bladder carcinoma in situ." (PMID 36288358, 2022). "HMGB3 promotes cell proliferation in bladder cancer and interacts with TOP2A and TOP2B, two targets for some anticancer agents." (PMID 28212608, 2017).
astrocytoma (2 papers, 2016 to 2022). "Results are consistent with previous findings showing increased sensitivity to H2O2 in astrocytoma cell line and to N-ethyl N-nitroso urea in granule neurons after Top2β silencing." (PMID 27462186, 2016).
B cell deficiency (2 papers, 2022 to 2025). A broad classification of disorders where circulating numbers of B lymphocytes are decreased or ineffective. "TOP2B plays a critical role in B-cell development and dominant pathogenic variants in TOP2B have been shown to lead to B-cell deficiency." (PMID 40656194, 2025). "Here, we report a Chinese girl who presented with IESS and B-cell deficiency caused by a de novo TOP2B variant." (PMID 40656194, 2025). "Although some of the TOP2B-deficient patients presented neurological defects, this trait has lower penetrance than B-cell deficiency, which was found in all patients." (PMID 36045673, 2022).
breast tumors (2 papers, 2014 to 2023). "This could be explained by the TOP2B expression in >90% of cells in breast tumors." (PMID 25406834, 2014).
COVID-19 (2 papers, 2022 to 2023). A disease caused by infection with severe acute respiratory syndrome coronavirus 2. "Among these proteins, KRT19, TOP2B, AREG, HGF, CKAP4, ITGB6, and NCF2 had a higher expression (> twofold) in plasma samples of severe compared to moderate COVID-19 patients, whereas CLEC4C and LTA were among the few proteins that were expressed at lower levels in severe patients." (PMID 36829233, 2023).
Intellectual disability (2 papers, 2017 to 2018). "Recent work involving clinical whole-exome sequencing identified a novel TOP2B mutation associated with intellectual disability, autistic traits, microcephaly, and developmental retardation and homozygous mutations in TDP2 have been linked with cases of intellectual disability, epilepsy, and ataxia." (PMID 29181194, 2017).
lymphoma (2 papers, 2024 to 2025). A malignant (clonal) proliferation of B- lymphocytes or T- lymphocytes which involves the lymph nodes, bone marrow and/or extranodal sites. "Docking was done on the crystallographic structures of 11 receptors known for their association with lymphoma; two receptors, DNA topoisomerase II-beta and PI3Kβ, were docked in duplicates as there are fine alternative crystallographic structures for them in the protein data bank." (PMID 39885875, 2025).
respiratory failure (2 papers, 2017 to 2018). The significant impairment of gas exchange within the lungs resulting in hypoxia, hypercarbia, or both, to the extent that organ tissue perfusion is severely compromised. "Although heterozygous Top2b+/− mice were indistinguishable from their wild-type littermates, homozygous Top2b−/− pups succumbed to respiratory failure shortly after birth." (PMID 29966298, 2018). "In the absence of Top2β phrenic MNs do not develop and mice die due to respiratory failure, while other MN subtypes are partially preserved, demonstrating a phrenic-specific critical role for Top2β." (PMID 29379870, 2017). "Top2β mutant mice show lack of diaphragm innervation and die at birth due to respiratory failure, but the mechanisms of Top2β action in MNs are not known." (PMID 29379870, 2017). "Mice lacking the Top2β gene lack diaphragm motor innervation that results in perinatal lethality due to respiratory failure." (PMID 29379870, 2017). "Since Top2β-/- mice die from respiratory failure due to lack of diaphragm innervation, we first examined whether they exhibit defects in PMC specification." (PMID 29379870, 2017).
retinal degeneration (2 papers, 2023 to 2025). Degeneration of the retina. "The resulting 44 Top2b-linked genes, dynamically expressed in retinal degeneration, were analyzed using custom Python code to query Reactome." (PMID 40558514, 2025). "All genes first had their gene symbols standardized, and the results were matched to determine which Top2b-linked genes were also associated with retinal degeneration in the literature." (PMID 40558514, 2025). "This review aims to uncover and categorize genes linked to Top2b that are dynamically expressed during retinal degeneration, revealing shared and overlooked regulatory pathways." (PMID 40558514, 2025). "By cross-referencing these genes with retinal degeneration datasets, including RetNet and the Gene Ontology Browser, we identified 44 Top2b-linked genes associated with retinal degeneration." (PMID 40558514, 2025). "While numerous pathways and genes have been implicated in retinal degeneration, the explicit pathway flows between Top2b were solely based on published data from GSE86187, RetNet, and the Gene Ontology Browser." (PMID 40558514, 2025). "Longitudinal studies in both animal models and human patients are also needed to uncover the intricate details of Top2b’s involvement in retinal degeneration." (PMID 40558514, 2025). "In transcription, the role of Crx is tightly regulated by Top2b, meaning tampering with this pathway can lead to transcriptional failure and subsequent retinal degeneration down the line." (PMID 40558514, 2025). "Dynamically expressed genes in the Top2b KO mice, present in at least one of the retinal degeneration datasets, were included in this study for pathway analysis." (PMID 40558514, 2025). "The outlined Crx pathway illustrates how transcriptional dysregulation can lead to retinal degeneration while demonstrating the possible target of Top2b-Crx for treating transcriptional defects in retinal diseases." (PMID 40558514, 2025). "All of these genes, powered by the regulatory activity of Top2b, can dictate the health of an individual’s retina, with all of these genes also holding the power to trigger retinal degeneration when its expression goes awry." (PMID 40558514, 2025). "The pathways identified through Reactome were divided into the functional categorization of genes and used to establish connections between Top2b regulation, retinal degeneration, and specific pathways." (PMID 40558514, 2025). "Pathways linking Crx to retinal degeneration have also been studied, allowing us to paint a bigger picture of Top2b’s role in retinal homeostasis and its cascade effects." (PMID 40558514, 2025). "Top2b activity alterations impair this transcriptional regulation, reducing the retina’s ability to respond to environmental and oxidative stressors, thus promoting retinal degeneration." (PMID 40558514, 2025). "Disruption of Top2b activity could impair the expression of Bbs7, exacerbating protein mislocalization and catalyzing retinal degeneration." (PMID 40558514, 2025). "In regard to the direct causality limitation, CRISPR-based validation of key regulatory relationships could establish causality in the Top2b network, while in another sense, pharmacological studies targeting Top2b modulation could assess potential therapeutic benefits in retinal degeneration models." (PMID 40558514, 2025).
acute promyelocytic leukemia (1 paper, 2016). An aggressive form of acute myeloid leukemia (AML), characterized by arrest of leukocyte differentiation at the promyelocyte stage, due to a specific chromosomal translocation t(15;17) in myeloid cells. "The effect is likely cell type specific, because Top2β has been shown to repress ATRA induced differentiation of acute promyelocytic leukemia cells towards granulocytes." (PMID 27462186, 2016).
BILU syndrome (1 paper, 2025). "The absence of retinal phenotypes in BILU syndrome patients and the embryonic lethality of complete TOP2B loss raise important questions about our findings’ translational relevance." (PMID 40558514, 2025).
brain tumors (1 paper, 2019). "In conclusion, our findings in the LN229 and primary GBM cells support a new approach for the therapy of brain tumors by targeting NMDAR-mediated Top2β-induced DSBs, which are required for regulating transcription." (PMID 30841565, 2019).
chronic myeloid leukemia (1 paper, 2017). "As expected, SA pretreatment did not affect stabilized TOP2A or TOP2B-DNA complexes in K562 cells, a chronic myeloid leukemia-derived cell line that does not express MPO." (PMID 27974636, 2017).
congenital heart disease (1 paper, 2020). A heart disease that is present at birth. "Large cohort investigations for congenital heart disease with NDDs or developmental disorders reported three de novo TOP2B variants, but their clinical descriptions are not available." (PMID 31953910, 2020).
epilepsy (1 paper, 2025). A brain disorder characterized by episodes of abnormally increased neuronal discharge resulting in transient episodes of sensory or motor neurological dysfunction, or psychic dysfunction. "Although epilepsy and neurodevelopmental disorders have been reported in patients with TOP2B deficiency, typical IESS has not been described previously." (PMID 40656194, 2025).
malignant glioma (1 paper, 2019). A grade III or grade IV glioma arising from the central nervous system. "Since ERG expression like cFos and EGR1 has been reported to correlate with radioresistance and poor prognosis in malignant glioma, we wondered if NMDAR signaling was also capable of regulating Top2β-dependent cFos expression in GBM cells." (PMID 30841565, 2019).
myelodysplastic syndrome (1 paper, 2020). A clonal hematopoietic disorder characterized by dysplasia and ineffective hematopoiesis in one or more of the hematopoietic cell lines. "Another reason to limit the clinical application of Top2β inhibitors is the strong unwanted side effects produced (secondary leukemia, myelodysplastic syndrome (MDS), and cardiac toxicity)." (PMID 33027952, 2020).
osteosarcoma (1 paper, 2013). A usually aggressive malignant bone-forming mesenchymal neoplasm, predominantly affecting adolescents and young adults. "Furthermore, the statistical trend between the worse EFS and TOP2B deletion population seems to link the induced malignant osteoblast growth to TOP2B downregulation, which is favoring the local osteosarcoma development." (PMID 24216996, 2013).
ovarian tumors (1 paper, 2014). "A predominance of TOP2B in the combined TOP2A/TOP2B activity has been also described in ovarian tumors." (PMID 25406834, 2014).
retinal diseases (1 paper, 2025). "To assess the clinical relevance of our list of Top2b-linked genes, we cross-referenced our 44 genes with human retinal disease databases (Appendix A Table A3)." (PMID 40558514, 2025). "Rather than suggesting TOP2B mutations cause retinal disease, our analysis reveals which retinal genes depend on Top2b for normal expression." (PMID 40558514, 2025).
thymic lymphomas (1 paper, 2020). "Finally, in order to reinforce the idea that the rearrangements found in thymic lymphomas could be related to 3D-genome folding and the functions of TOP2B in this process, available Hi–C maps on wild-type thymocytes 41 were integrated with hotspots of Atm−/−-linked genomic instability." (PMID 32060399, 2020).